TNF (tumor necrosis factor)
Diseases named in the same sentence as TNF in open-access papers (continued):
Sharing a sentence is not in itself a finding about the gene and the disease.
autoimmune thyroid disease (37 papers, 2014 to 2026). Inflammatory disease of the thyroid gland due to autoimmune responses leading to lymphocytic infiltration of the gland. "In line with our explanation, its translocation and membrane expression were blocked by proinflammatory cytokines associated with thyroid autoimmunity: interleukin-1ß, tumor necrosis factor-α, and interferon-γ." (PMID 38051473, 2024). "Consequently, TNF-α has been proposed as a therapeutic target for autoimmune thyroid disease linked to Th17/Th1 imbalance." (PMID 40342407, 2025). "Chronic inflammation in autoimmune thyroid disease is characterized by elevated pro-inflammatory cytokines (e.g., IL-6, TNF-α), which can suppress hepatic enzyme production or alter their release kinetics." (PMID 40978853, 2025). "Central to its pathogenesis is the TNF-IL-23-IL-17 axis, which also plays a pivotal role in autoimmune thyroid diseases such as GD and HT." (PMID 40922376, 2025). "For instance, IL1B was involved in mismatch repair, PTGS2 participated in the IL-17 signaling pathway and TNF signaling pathway, SELL was associated with autoimmune thyroid disease, and notably, all three genes were related to tyrosine metabolism." (PMID 40857330, 2025). "This is consistent with the observed reduction in RAI uptake in DTCs with concurrent thyroiditis, as TNF-α is a central factor in thyroid autoimmunity." (PMID 32049985, 2020). "Tumor necrosis factor- (TNF-) related apoptosis-inducing ligand (TRAIL) protein is another molecule possibly contributing to the autoimmune thyroid disease." (PMID 25784936, 2015). "Adipose tissue is an active endocrine organ that secretes pro-inflammatory cytokines such as TNF-α, IL-6, and leptin, which may exacerbate thyroid autoimmunity and contribute to ovarian dysfunction." (PMID 41303060, 2025). "Leptin-induced inflammation and the presence of inflammatory cytokines like TNF-α and IL-6 within the thyroid gland may contribute to the development of thyroid autoimmunity." (PMID 38567309, 2024). "KEGG enrichment analyses showed that these IBD/UC-risk genes from the MC group were enriched in intestinal immune network for IgA production and autoimmune thyroid disease, while the IBD/UC-risk genes from the MCI group were enriched in TNF/IL-17 signaling pathways." (PMID 35133977, 2022). "Interestingly, NIS expression can be negatively regulated by TNF-α, a bona fide activator of NF-κB with a central role in thyroid autoimmunity." (PMID 32049985, 2020). "TNF-α expression has also been shown to be increased in patients with autoimmune thyroid disease, and therefore, treatment with TNF-α inhibitors could possibly effect thyroid autoimmune status as well." (PMID 28824542, 2017). "In addition, LPS increases the expression of tumor necrosis factor-α (TNF-α) in rat thyroid cells, while serum TNF-α levels are associated with TG-Ab levels in patients with HT, and serum TNF-α levels are also increased in patients with SCH due to autoimmune thyroiditis." (PMID 41170176, 2025). "The role of tumor necrosis factor alpha (TNF-alpha) is crucial in the CD pathogenesis, but also in thyroid autoimmune diseases." (PMID 39968296, 2025). "In autoimmune thyroid disease, IFN-γ and TNF-α were consistently reported to synergize in the induction of the chemokine CXCL10 secretion by thyrocytes." (PMID 34224085, 2021). "Based on the results in the present review, alterations in thyroid autoimmune status upon anti-TNF-α treatment seem to be a minor concern and may very well be overshadowed by the potential benefit of such treatment—both in regard to the rheumatoid disease and possibly the thyroid autoimmune status." (PMID 28824542, 2017). "However, benefits of biological treatment, that is, tumor necrosis factor (TNF) inhibitors to regulate and even depress thyroid autoimmunity, has been discussed recently, which delineates the possible role of TNF-α in a shared pathology between RA and thyroid autoimmunity." (PMID 29069018, 2017).
autoimmune thyroid disease (continued). "Autoimmune thyroid diseases (e.g., Hashimoto’s thyroiditis and Graves’ disease) are among the most common comorbidities and are typically characterized by the overproduction of IFN-γ and TNF-α." (PMID 40430113, 2025).
B-cell lymphoma (37 papers, 2008 to 2025). "Mutations in the glucocorticoid receptor regulatory network pathway tended to occur early, while mutations in the TNF pathways were more likely to occur late in B-cell non-Hodgkin lymphoma." (PMID 39868264, 2025). "Mutations in the glucocorticoid receptor regulatory network pathway, including CREBBP, tended to occur early, while mutations in the TNF pathways tended to happen late in B-cell non-Hodgkin lymphoma." (PMID 39868264, 2025). "The TNF pathway, a positive regulator of tumor cell response to T-cell killing, exhibited mutations in 12.5% of B-cell non-Hodgkin lymphomas." (PMID 39868264, 2025). "A study analysing point mutations in B cell lymphoma identified a S525 mutation that reduces TNFα and IKKα induced c-Rel reporter activity." (PMID 26999213, 2016). "Mutation of S525 conferred resistance to TNFα-induced apoptosis suggesting that this mutation may contribute to the development of B cell lymphoma in humans." (PMID 26999213, 2016). "Furthermore, TNF-857T alleles are associated with an increased risk of B-cell lymphoma." (PMID 39451257, 2024). "The development of B-cell lymphoproliferative diseases in BAFF-Tg mice appears to be linked to the action of tumor necrosis factor (TNF), as introducing TNF deficiency into a BAFF-Tg background increases the incidence of B-cell lymphoma." (PMID 39222149, 2024). "A previous study showed dysregulated circulating cytokines (such as IL5, IL13, TNF, etc.)were correlated with B-cell non-Hodgkin lymphoma." (PMID 35452413, 2022). "It has been further reported that TNFα-induced apoptosis can be regulated via an ADAM10-NF-κB feedback loop in a B cell lymphoma cell line." (PMID 33791311, 2021). "Apart from helper T cells, various cell types of the B cell lymphoma microenvironment are capable of producing the cytokines IL-4, IL-6, IL-10 and TNFα." (PMID 32899476, 2020). "In mantle-cell lymphoma (MCL), a type of aggressive B cell non-Hodgkin’s lymphoma, which is frequently resistant to conventional chemotherapies, fenofibrate efficiently induced apoptosis through the downregulation of tumor necrosis factor (TNF) α." (PMID 35954274, 2022). "However, there are case reports of primary intraocular B-cell lymphoma arising during methotrexate and tumor necrosis factor inhibitor treatment." (PMID 29954352, 2018). "Moreover, specific TNF-α haplotypes were observed to promote the progression of B-cell lymphomas." (PMID 39046819, 2024). "B-cell NHLs frequently express CD27/CD27L (TNFRSF7/TNFSF7), CD30 or CD30L (TNFRSF8 or TNFSF8), CD40 (TNFRSF5), and TNFRs/TNF positive (TNFRSF1 and 2/TNFSF2), but T-cell NHLs show expression of CD30, CD40L (TNFSF5), and TNFRs/TNF." (PMID 37240076, 2023). "CD30 is a transmembrane glycoprotein, a member of the tumor necrosis factor (TNF) superfamily and it is expressed in activated B and T cells, and, commonly, in HL, ALCL, and a small proportion of B cell lymphomas." (PMID 36654819, 2022). "The increased levels of TNF-α, IL-12 and IFN-γ and undetectable levels of IL-4 and IL-10 suggest that TME in lacrimal gland B-cell lymphoma was polarized toward Th1 pattern, which is similar to what were previously observed with an intraocular B-lymphoma." (PMID 29029511, 2017). "In immortalized chondrocytes, NFκB-DNA binding activity is dependent on TNFα-induced MEK/ERK signalling, consistent with studies in other immortalized cells such as B-cell lymphoma cell lines." (PMID 19144181, 2009). "MYC overexpression is also inversely correlated with tumor necrosis factor (TNF) super family members lymphotoxin-α(TNFSF1), lymphotoxin-β and TNF-α, that play a role in T cell recognition, cell-to-cell communication and adhesion in B cell lymphoma cell lines." (PMID 33092116, 2020). "Surprisingly, LITAF did not induce TNF secretion upon LPS stimulation in B-cell lymphomas, and subcellular localization determined LITAF to be cytoplasmic only." (PMID 27764808, 2016).
B-cell lymphoma (continued). "Indeed, while FasL expression by astrocytes induces cell death in infiltrating lymphocytes, B cell–activating factor of the tumor necrosis factor (TNF) family (BAFF) produced by astrocytes promotes B-cell survival in inflammatory conditions and primary B cell lymphoma." (PMID 33117368, 2020). "Therefore we did not expect to see any increase of B cell lymphoma incidence in RA patients under TNF inhibitors." (PMID 28199343, 2017).
brain tumor (37 papers, 2011 to 2025). "Increased serum levels of TNFα and IL-1β in patients with brain tumors have been associated with adverse prognosis." (PMID 37542119, 2023). "Similar with the myeloid cells of adult brain tumors, myeloid cells of medulloblastoma were significantly enriched in oxidative phosphorylation and TNFα pathways while deficient in hypoxia signals." (PMID 38094301, 2023). "None of the recombinant TNF proteins were cytotoxic, and TNF-alpha significantly increased both USP7 and USP13 confluence, indicating that soluble TNF-alpha enhances brain tumour cell growth." (PMID 40240536, 2025). "Collectively, our results indicate that TNF-alpha holds promise as a potential prognostic marker for brain tumour oZIKV therapy." (PMID 40240536, 2025). "In the context of brain tumors, although resident antigen-presenting microglia express TLRs, they are unable to secrete interleukin (IL)-1B, IL-6, or tumor necrosis factor-alpha (TNF-α) to mount an effective innate immune response." (PMID 38256021, 2024). "In humans, the proinflammatory cytokines IL-1β, IL-6, IL-8, IL-12, GM-CSF and TNF-α have been involved in brain tumor initiation and progression." (PMID 36232813, 2022). "THBO is also said to enhance the inflammatory response in brain tumor patients by reducing TNF-α and IL-6 levels, reducing mean cerebral artery flow, and effectively reducing cerebral artery spasm." (PMID 34790416, 2021). "TILs isolated from brain tumor-bearing mice treated with anti-PD-1, Poly(I:C), and anti-PD-1+Poly(I:C) had a significantly higher percentage of OT-1 divided cells that produced TNF-α." (PMID 29755681, 2018). "We observe conserved TNF signalling and cytokine signalling-related signatures and show that the TNF-alpha signalling pathway is implicated in oncolysis by reducing the viability of ZIKV-infected brain tumour cells." (PMID 40240536, 2025). "Thus, the clinical utility of TNF-alpha in paediatric brain tumour therapy and OV therapy requires further delineation." (PMID 40240536, 2025). "Here, we show that TNF-alpha (i) is a brain tumour cell growth factor, (ii) may sensitise brain tumour cells to oncolysis by augmenting ZIKV-induced reduced cell viability, and (iii) is a marker of poor prognosis for medulloblastoma." (PMID 40240536, 2025). "Thus, TNF-alpha is a marker of poor prognosis for medulloblastoma patients, possibly by enhancing brain tumour cell growth." (PMID 40240536, 2025). "Additionally, our current findings have the potential to alter the clinical use of CDDP in medulloblastoma patients and should influence targeted systemic TNFα therapy in this type of brain tumor." (PMID 37331004, 2023). "Moreover, IL-6, IL-8, and TNFα resulted in being overexpressed in the serum of adult and pediatric patients affected by brain tumors." (PMID 35335997, 2022). "TNF reduces brain tumor growth by enhancing macrophage recruitment and microcyst formation." (PMID 31186453, 2019). "Like IL-1B also the enhanced expression of TNF might induce IL-6 and subsequently reduce brain tumor growth by enhancing macrophage recruitment." (PMID 30224928, 2018). "On the other hand, the presently observed combined downregulation of NO and TNF along with the upregulation of ROS allows us to hypothesize that H2S donors may be useful for the treatment of + certain brain tumors such as GBM." (PMID 30441775, 2018). "We found that TNF-α treatment could help breach the blood-brain barrier and result in major accumulations of 125I-labeled SSLs in the orthotopically implanted brain tumors as well as significantly prolong the survival of the tumor-bearing animals." (PMID 21378416, 2011).
brain tumor (continued). "For example, malignant brain tumor cells have been observed to utilize astrocyte gap-junctional network to transfer the second messenger cGAMP to activate and produce inflammatory factors, interferon alpha (IFNα) and tumor necrosis factor (TNF) via the STING signaling pathway in astrocytes." (PMID 35513201, 2022). "Extending our TNF ELISA assays to a 49-plex ELISA, we sought to validate the cytokine-related transcriptomic signatures enriched in ZIKV-infected brain tumour cells." (PMID 40240536, 2025). "Here, our multi-omics analysis highlighted the involvement of TNF and cytokine signalling as indicators of ICD in ZIKV-infected childhood brain tumour cells." (PMID 40240536, 2025). "We show the upregulation of multiple TNF-TNFR signalling pathways following infection, and we identify TNF-alpha as a potential prognostic marker for brain tumour oZIKV therapy." (PMID 40240536, 2025). "In ZIKV-infected paediatric brain tumour cells, we observe transcriptomic signatures indicative of ICD, TNF pathway and cytokine signalling responses." (PMID 40240536, 2025). "There were substantial similarities between retro-orbital/brain tumors and tRCC, including EMT, lysosome, inflammation (inflammatory response, TNF-α/NF-κB, allograft rejection), and cell proliferation (E2F, Myc, cell cycle, DNA replication, mitotic spindle)." (PMID 38386415, 2024). "We found that the frequencies of IFN-γ-, TNFα-, and IL-2-producing CD4+ T cells were increased in the brain tumour, spleen, and blood of EMP3_KO model mice." (PMID 33964937, 2021). "TNF and pro-inflammatory cytokine signalling are principal outcomes of ICD, and we observe terms related to these as the top two significantly enriched KEGG pathways in ZIKV-infected brain tumour cells at 24 hpi." (PMID 40240536, 2025). "When we evaluated the percentages of IFN-γ-, TNF-α-, and IL-2-producing CD4+ and CD8+ T cells within GBM tumours, we noticed that CXCR3 blockade in the EMP3_KO group reduced CD8+ and CD4+ T cell infiltration into the brain tumour, blood, and spleen." (PMID 33964937, 2021). "We also evaluated the percentages of CD8+ and CD4+ T cells within the tumour, blood, and spleen and found that anti-PD-1 treatment of EMP3_KO tumour-bearing mice increased IFN-γ-, TNF-α- and IL-2-producing CD8+ and CD4+ T cell infiltration into the brain tumour, blood, and spleen." (PMID 33964937, 2021). "Following stereotactic injection of GL261 cells into the frontal lobe, brain tumors were allowed to grow to substantial size, then 125I-labeled SSLs with or without TNF-α were administered." (PMID 21378416, 2011). "Interestingly, recombinant TNF-alpha reduces cell viability of ZIKV-infected brain tumour cells, suggesting that in the context of oZIKV therapy, TNF-alpha is anti-tumoural as it enhances brain tumour cell oncolysis by ZIKV." (PMID 40240536, 2025). "Surprisingly, cytokines (TNF, Jak/STAT) that often mediate macrophage-epithelial tumor signaling were not activated in this brain tumor." (PMID 37549261, 2023). "hAMSCs did not affect brain tumor cell proliferation, in vivo Ki-67 (proliferative marker) expression in GBM, or GBM expression of TNF-α, a necrosis marker." (PMID 25501828, 2014).
chlamydial infection (37 papers, 2006 to 2025). "For example, the levels of granzyme were significantly higher during the chlamydial infection in TNF-α deficient mice when compared to WT animals." (PMID 23483844, 2013). "The aim of our study is to evaluate the mechanistic role of TNF-α in clearance of primary and secondary chlamydial infection from the genital tract (GT) using C57BL/6 TNF-α deficient (TNF-α−/−) and wild type (WT) mice." (PMID 23483844, 2013). "There is evidence to suggest that the elevated local levels of TNF and IL-1β associated with chlamydial infection and inflammation act as an important trigger of matrix degradation by inducing MMP-9 activity in inflamed tissue." (PMID 16643654, 2006). "Chlamydial infections such as C. pneumoniae developed immune events through the INFα/β, TNF-α, MAPK/ERK, NLRP3/ASC/caspase- 1, JAK/STAT, PI3 K/Akt signaling pathways." (PMID 40275124, 2025). "In response to chlamydial infection, TNF-α leads to a reduction in chlamydial growth by cooperating with IFN-γ, which results in an increased activity of indoleamine 2,3-dioxygenase (IDO) and inhibition of host cell metabolism." (PMID 40647668, 2025). "This study demonstrated a preferential increase in M1-type macrophages in the lungs of mice following chlamydial infection with higher expression of iNOS and TNF-α." (PMID 38247825, 2024). "We also assessed the systemic response by splenic T cells expressing cytokines with known importance to resolution of chlamydial infections and pathology; IFNγ, TNFα, IL17, IL13, IL10." (PMID 36799886, 2023). "Deficiency of TLR2 or TLR4 in macrophages significantly reduces TNF-α levels during chlamydial infection,while deficiency of TLR3 in epithelial cells increases its levels at the early stage of chlamydial infection." (PMID 34093528, 2021). "In genital chlamydia models, it has been shown that the enhancement of TNFα is also required for achieving protection against chlamydia and mechanisms that are nearly IFNγ independent but dependent on Plac8 and likely on T cell degranulation exist as well." (PMID 28678871, 2017). "In DCs, chlamydia-infection as well as TNF-α or AA treatment strongly up-regulate glycolysis, which maintains ATP production despite the loss of functional mitochondria." (PMID 28634388, 2017). "Production of TNF-α has also been shown to participate in the clearance of chlamydial infection, potentially via up regulation of IFN-β, NK cells or neutrophils." (PMID 28575080, 2017). "Together, our study suggests CXCR3 regulate CD8, CD8+TNF-a+ and neutrophils, those cells are involved or partially involved in inducing tissue pathology following chlamydial infection." (PMID 29552679, 2017). "In summary, this first report reveals that CXCR3 not only regulates Th1 T cell activation and trafficking, but also modulates CD8+TNF-a+, cDC, pDC, neutrophil and NK cells in chlamydial infection." (PMID 29552679, 2017). "In a similar fashion, the role played by TNF-α in chlamydial infection has provided disparate results." (PMID 27219467, 2016). "We also detected an increase of MIF/GIF after chlamydial infection, a pro-inflammatory cytokine promoting the production of tumor necrosis factor (TNF), IFN-γ, IL-1β, IL-2, IL-6 and IL-8." (PMID 25019934, 2014). "On average, IL10 mRNA expression levels were observed to be higher (P<0.05) than TNFα mRNA expression levels in Group I animals (with current chlamydial disease)." (PMID 23527290, 2013). "In a preliminary study to evaluate the role of these cytokines in koala chlamydial infections and disease, TNFα and IL10 responses of koala PBMCs, isolated from three cohorts of koalas was measured." (PMID 23527290, 2013). "Following both primary and secondary genital chlamydial infection, TNF-α−/− mice exhibited elevated granzyme B production, but similar IFN-γ and antibody responses." (PMID 23483844, 2013).